LDHA (lactate dehydrogenase A)
Diseases named in the same sentence as LDHA in open-access papers (continued):
Sharing a sentence is not in itself a finding about the gene and the disease.
tumor (continued). "have proposed that this possible mechanism is hypoxia in tumor tissue, and the reduction of LDHA may affect cellular oxygen consumption and cell activity." (PMID 38264652, 2023). "In addition, we transfected the FOXK2-142aa overexpression vector and si-LDHA into HCC cells and found that the exogenous knockdown of LDHA expression significantly weakened the pro-tumor effects of FOXK2-142aa." (PMID 36922872, 2023). "Studies suggest that the combined use of LDHA and PD-1 inhibitors could improve the latter's efficacy by reducing the amount of lactate produced by tumor cells." (PMID 37679788, 2023). "Interestingly, when the activity of miRNA was finished, the activity of LDHA was restored to baseline levels, favoring cell proliferation and invasion, demonstrating the importance of the expression of this gene for the tumor neoplastic phenotype." (PMID 37326348, 2023). "Scientists have discovered that LDHB is consistently expressed in different types of cancer cells, whereas LDHA may play an important role in tumor initiation since it is frequently overexpressed in cancer." (PMID 37415191, 2023). "Hypoxia conditions in the tumor microenvironment are reflected in HIF1α and LDHA expression." (PMID 36900270, 2023). "Furthermore, knocking down LDHA can neutralize tumour pH and reduce the Treg/Teff ratio, culminating in improved response to ICIs and enhanced tumour control." (PMID 37234284, 2023). "LDHA knockdown attenuated tumor metastasis by inhibiting epithelial-mesenchymal transition (EMT)." (PMID 37547725, 2023). "Tumor-derived lactate plays several roles in tumor development, including serving as a proinflammatory mediator that increases cytokines such as IL-1ß, and lactate dehydrogenase A (LDHA) is integral in producing lactate." (PMID 38173841, 2023). "In a study on TNBC, Xing collected tissues from TNBC patients for examination and found that circPDCD11, a sponge of miR-432-5p, upregulated LDHA in triple negative breast cancer, and further experiments showed that knockdown of circPDCD11 effectively inhibited tumor growth." (PMID 37204526, 2023). "It was previously reported that LDHA promoted tumor growth and enhanced cancer cell metabolism." (PMID 37398901, 2023). "In addition, CPT1A promotes lysine residue k222 succinylation of lactate dehydrogenase A (LDHA), which is associated with tumor cell proliferation and poor prognosis of patients." (PMID 37777749, 2023). "In addition, the glucose ingested by tumor cells can be metabolized into lactate using lactate dehydrogenase A (LDHA) during glycolytic metabolism." (PMID 38139250, 2023). "In short, circRARS can promote glycolysis and tumor progression in NSCLC by regulating LDHA." (PMID 36628612, 2023). "We studied the expression of PD-L1 in a series of 66 PCs, in parallel with the expression of hypoxia- and acidity-related immunohistochemical markers (Hypoxia-inducible factor HIF1α, and lactate dehydrogenase LDHA) and tumor-infiltrating lymphocyte TIL density." (PMID 37067635, 2023). "While various studies have revealed that the suppression of LDHA gene expression cripples tumor cell proliferation both in vitro and in vivo, it has also been suggested that the complete inhibition of the tumor growth can only be achieved through simultaneous disruption of both LDHA and LDHB genes." (PMID 37868977, 2023). "Tumor cells overexpress LDHA to obtain energy through aerobic glycolysis." (PMID 37898799, 2023). "Furthermore, nuclear LDHA levels were higher in tumor tissues than in normal tissues from various organs and different for various cell lines of the same tumor." (PMID 37779146, 2023). "Additionally, an increase in LDHA protein level was detected by immunoblot analysis in the lysates of MC-38 isografted tumor tissue from HCD and HFD mice as compared to ND control mice." (PMID 37705114, 2023).
tumor (continued). "Notably, also LDHA/LDHB expression ratio—measured within each tumour sample—shows a marked increase only in BRAF-like tumours, whereas LDHB is modestly upregulated in the RAS-like subtype." (PMID 37198319, 2023). "Previous report demonstrated that LDHA blunts tumor immunosurveillance by CD8+ T cells." (PMID 36923931, 2023). "LDHA has a key role in tumor metabolism, but how malignant cells adapt to LDHA inhibition remains unclear." (PMID 36588153, 2023). "Finally, IHC analysis based on CRC specimen revealed that APOL3 expression was positively correlated with CD8+ T cell infiltration with R2 of 0.58 and negatively correlated with tumor LDHA expression with R2 of 0.17." (PMID 36923931, 2023). "Considering the importance of the neoplastic phenotype and tumor metabolism, LDHA could be a promising therapeutic target in CC." (PMID 37326348, 2023). "Furthermore, mechanistic studies indicated that FOXQ1 promotes LDHA transcription, and thus modulates aerobic glycolysis to enhance PC cell proliferation, tumor stemness, invasion, and metastasis by increasing LDHA expression." (PMID 37875474, 2023). "Thus, pharmacological inhibition of LDHA suppressed tumor growth along with CAF reduction and reversed the immunosuppressive status of CAF-rich PDAC tumors through reductions in the levels of lactate and IL-6." (PMID 37733442, 2023). "Finally, the LDHA inhibitor FX11 reduced tumor growth and improved antitumor immunity in CAF-rich PDAC tumors." (PMID 37733442, 2023). "As a result, increased LDHA activity promotes tumor progression." (PMID 35278714, 2023). "LDHA has been reported to promote tumor cell growth in the past." (PMID 37733442, 2023). "The CENPE was upregulated while LDHA was downregulated in tumor tissues." (PMID 37925501, 2023). "Similarly, the hypoxic nature of the TIME drives upregulation of LDHA in CD8+ tumor-infiltrating lymphocytes (TILs), leading to excess intracellular lactic acid, which then inhibits IFNg and granzyme B production and T cell expansion." (PMID 37842241, 2023). "Previous evidence suggests that LDHA mediate tumor spread, invasion, and progression and may be a promising therapeutic target." (PMID 36447119, 2023). "It has been found that high lactate levels inhibit T cell functions, including interleukin-2 secretion and T cell receptor activation, while blocking lactate dehydrogenase A in tumor cells improves immune function and the efficacy of anti-programmed cell death 1 therapy." (PMID 38139250, 2023). "LDHa expression, upregulated by cMYC, enhances aerobic glycolysis and promotes tumor expansion." (PMID 38201518, 2023). "Flow cytometry analysis of harvested tumor indicated that the analysis observed that the infiltration of MDSCs significantly reduced in KPC-ABHD17C-OE-LDHA-KD group than that in KPC-ABHD17C-vector-LDHA-Ctrl group." (PMID 37273016, 2023). "HK2, PDK1, and LDHA are also reported to be key participants in the tumor glycolysis process." (PMID 37233956, 2023). "As discussed, tumor cells are capable of glucose metabolic alteration from oxidative phosphorylation to cytoplasmic glycolysis; pyruvate dehydrogenase kinases (PDKs) and lactate dehydrogenase A (LDHA) are crucial enzymes in this occurrence." (PMID 37046703, 2023). "In addition, LDHA was another key glycolytic enzyme and was considered a potential anti-tumor therapeutic strategy." (PMID 37588107, 2023). "Similarly, other studies have demonstrated that the knockdown of lactate dehydrogenase A in tumor cells improves the efficacy of CAR T cell therapy and significantly reduces tumor growth." (PMID 38139250, 2023). "Furthermore, in different works, it was shown that nuclear PKM2 interacts with hypoxia-inducible factor-1α (HIF-1α), thus increasing the expression of its target genes (such as GLUT1 and LDHA) and providing metabolic reprogramming of tumour cells." (PMID 37449059, 2023).
tumor (continued). "Besides, the expression of glycolytic enzymes, including GLUT1, HK2, and lactate dehydrogenase A (LDHA) was more in tumor cells after co-culture with TAMs." (PMID 35986343, 2022). "Studies in tumor metabolism revealed that B7-H3 increases the expression levels of hypoxia-inducible factor 1 α (HIF1α), lactate dehydrogenase A (LDHA), and pyruvate dehydrogenase kinase 1 (PDK1), and therefore stimulates the Warburg effect by increasing glucose uptake and lactate production." (PMID 36159789, 2022). "In the same tumor type, LDHA, is downregulated by miR-34a-5p, together with PKM2." (PMID 35348905, 2022). "LDHA contributes to the regeneration of NAD+ during the reduction of pyruvate to lactate, which is critical for ongoing glycolysis; meanwhile, elevated lactate level is associated with tumor cell proliferation, angiogenesis, and invasion." (PMID 36297369, 2022). "LDHA expression reported as either mRNA level or as protein levels determined by Western blots or by immunohistochemistry can provide information on LDH availability, which has been associated with the malignant state of the tumor." (PMID 35406616, 2022). "(v) LDHA inhibition by an inhibitor FX11 inhibits BCPAP tumor growth." (PMID 36557253, 2022). "However, it results in a reaction shift from lactate oxidation to pyruvate reduction and regeneration of NAD+ (similar to LDHA), promoting glycolysis, lactategenesis, and tumor growth." (PMID 36551514, 2022). "Furthermore, immunohistochemical staining was applied to evaluate the expression of KCNK3, proliferation marker Ki67, and the glucose metabolism GLUT1/LDHA in tumor tissue sections." (PMID 35963847, 2022). "As the miR-34 family can target LDHA directly, it was proposed that its role in tumor suppression could involve restricting glycolysis." (PMID 35205318, 2022). "Additionally, LINC01123 has been demonstrated to induce HK2 expression and LDHA expression, thereby enhancing lactate production and promoting the proliferation of tumor cells through the miR-199a-5p/c-Myc axis in NSCLC." (PMID 35757505, 2022). "In vivo and in vitro studies showed that miR-223 promotes tumor growth and these effects are associated with the negative regulatory effects of Fbw7-mediated ubiquitination of LDHA." (PMID 35359405, 2022). "Gossypol has shown anti-tumor activity based on various mechanisms of action, including suppression of anti-apoptotic proteins from the Bcl-2 family, cell cycle arrest, autophagy, and LDHA inhibition." (PMID 35628385, 2022). "While LDHA overexpression induced a pro-tumorigenic phenotype with autophagy inhibition, upregulation of EMT and cell proliferation, induction of autophagy from LDHA knockdown or FX11 also promotes a pro-tumorigenic phenotype by inhibiting apoptosis in tumor cells." (PMID 35846375, 2022). "Thus, LDHA had the potential to regulate tumor metabolism, control apoptosis and cell proliferation." (PMID 36568220, 2022). "In addition, the National Cancer Institute's Clinical Proteomic Tumor Analysis Consortium (CPTAC) dataset presented a similar pattern of LDHA protein expression to its mRNA trend in TCGA." (PMID 35637958, 2022). "Knocking down of LDHA can induce apoptosis and stop the growth of tumor cells." (PMID 36568220, 2022). "In addition, downregulation of FBP2 notably reduced FBP2 protein expression and upregulated Ki67, GLUT1, HK2, PKM2, and LDHA protein expressions in tumor tissues." (PMID 35571245, 2022). "As the last enzymatic step in the glycolytic pathway, a key part of lactate production involves efficient functioning of lactate dehydrogenase, especially LDHA, which is crucial in tumour growth and metastasis, such as lung cancer, liver cancer, breast cancer and PCs." (PMID 36578477, 2022). "Moreover, LDHA mRNA expression in tumor tissues was negatively correlated with miR-28-5p expression." (PMID 36109751, 2022).
tumor (continued). "In contrast, the high levels of LDHA observed in the tumor tissue of both advanced stages of CRC would suggest a clear Warburg effect, which indicates that aerobic glycolysis would also be supplying energy to promote and maintain the metastatic stage in the human CRC." (PMID 35205159, 2022). "In addition, among cyclic lactate catabolism, lactate dehydrogenase A (LDHA) can promote the tumor cells chemotherapy resistance." (PMID 35616278, 2022). "The overexpression of the metabolic enzyme LDHA is necessary for tumor growth and progression." (PMID 35982980, 2022). "Similarly, down-regulation of LDHA by an inducible KD approach decreases cell viability, clonogenic activity and tumor growth, and increases radio-sensitivity of an ATC cell line Hth83." (PMID 36557253, 2022). "The combination of LDHA depletion with anti-human prostate-specific membrane antigen (hPSMA)-Chimeric antigen receptor T cell therapy could significantly retard tumor growth." (PMID 36518315, 2022). "Molecular mechanism studies indicated that LDHA plays critical roles in tumor maintenance and aggravation, including promoting cancer cell proliferation, epithelial to mesenchymal transition, angiogenesis, cytoskeletal remodeling, cell motility, invasion and metastasis." (PMID 36072431, 2022). "MRI-derived tumour [1-13C]lactate labelling correlated with epithelial mRNA expression of the enzyme lactate dehydrogenase (LDHA and LDHB combined), and the ratio of lactate transporter expression between the epithelial and stromal compartments (epithelium-to-stroma MCT4)." (PMID 35075123, 2022). "Several studies have shown that lactate and LDHA contribute to tumor progression." (PMID 36698888, 2022). "Moreover, some small-molecule LDHA inhibitors play a marked effect on tumor burden, metastases, and cell death." (PMID 36518315, 2022). "In addition, based on IHC, expression levels of CDCA5, Ki67, p-mTOR, and LDHA were higher in tumor tissue generated by TPI1 overexpression cells than vector control; E-cadherin was lower in these tumors." (PMID 35509067, 2022). "Moreover, the extent of CD8+ stromal tumor-infiltrating lymphocytes (sTILs) inversely correlated with the LDHA expression when used as a continuous variable (Pearson rho = -0.37, p = 0.01)." (PMID 36505421, 2022). "Correspondingly, LDHA inhibition is shown to impair tumorigenesis and tumor growth." (PMID 36072431, 2022). "Furthermore, IHC assays indicated that PDK1, LDHA, and c-myc were upregulated in circPDK1-WT-overexpressing the subcutaneous tumor." (PMID 36068586, 2022). "The anti-tumour effects of Rec8 are caused by downregulation of cell growth-related genes (G6PD, SLC2A1, NOL3, MCM2, SNAI1, and SNAI2) and also by upregulation of both apoptosis or migration inhibitors (Gadd45G and LDHA) and tumour inhibitors (PinX1, IGFBP3, and ETS2)." (PMID 36139540, 2022). "In mouse models, targeting LDHA inhibits tumor growth and leads to delayed metastasis formation." (PMID 35362044, 2022). "Because of the high concentration of lactic acid, LDH enzymes with higher M-subunit contents (LDHA proteins) are abnormally overexpressed in a variety of cancers, increasing lactic acid levels and promoting tumor metastasis and invasion, as well as mediating tumor immune escape." (PMID 36276846, 2022). "However, few studies have evaluated the response changes of immune cells in the context of LDHA inhibitors in tumor treatment." (PMID 36518315, 2022). "Within B16.F10 tumors, LDHA, the enzyme that converts pyruvate to lactate, was detected in close proximity to lymphatic vessels, supporting the hypothesis that tumor-derived lactate drains to TDLNs where it may influence FRC behavior." (PMID 35362044, 2022). "Taken together, these results indicate that LINC01128 may act as a crucial tumor promoter of PC by competitively binding to miR-561-5p and subsequently upregulating the expression of LDHA." (PMID 35193567, 2022).
tumor (continued). "Additionally, a role for nuclear LDHA in promoting aggressive tumor phenotype is also suggested based on enhanced nuclear expression which was observed only in GBM." (PMID 33996536, 2021). "Based on these findings, it can be suggested that the inhibition of LDHA activity may confer sensitivity in tumor cells to DNA damaging agents." (PMID 33834022, 2021). "Using in vitro and in vivo methods, we explored the tumor‐promoting role of the LDHA gene in PAAD." (PMID 34185423, 2021). "Additionally, LDHA participates in tumor immunity by promoting upregulation of PD-L1 on tumor cells to impede effector T cell activity." (PMID 34852326, 2021). "However, the specific molecular mechanism of the involvement of LDHA in tumor immune regulation is still unclear, and further research is needed to confirm this." (PMID 34307169, 2021). "For instance, whether the circSLIT2/miR-510-5p/c-Myc/LDHA pathway takes effect in tissue in vivo, including xenograft tumor tissues, still needs further verification." (PMID 34168116, 2021). "LDHA is commonly overexpressed in cancer cells, leading to an excessive accumulation of lactate and promoting its secretion by the monocarboxylate transporters (MCTs) which, in turn, increases the acidification of the tumor microenvironment." (PMID 34208670, 2021). "Recently, accumulating evidence showed that the overexpression of LDHA could promote the production of lactate, thus contributing to the acidification of the tumor microenvironment, which may limit the effect of anti-PD-L1 therapy." (PMID 33858449, 2021). "Inhibiting LDHA with compound FX11 decreased ATP levels, reduced mitochondrial membrane potential, increased oxidative stress linked to cell death, activated AMPK, and inhibited tumor xenograft progression in transformed human B cell lymphoma." (PMID 33718271, 2021). "We could demonstrate that, similar to the LDH inhibitors, a LDHA/B double knockout significantly reduced the intracellular HSP levels in different tumor cell types." (PMID 34359663, 2021). "A number of aggressive human malignant tumors are characterized by an intensified glycolytic rate, over-expression of lactic acid dehydrogenase A (LDHA), and subsequent lactate accumulation, all of which contribute toward an acidic peri-cellular immunosuppressive tumor microenvironment (TME)." (PMID 34944395, 2021). "Various preclinical studies have shown that blocking LDHA to reduce glycolysis could inhibit tumor growth and metastasis, presumably indicating LDHA as a potential therapeutic target." (PMID 35127473, 2021). "Likewise, targeting LDHA induced immunosurveillance has been shown to be mediated by T and NK cells in mouse tumor models." (PMID 33413697, 2021). "Using immunodeficient mice, we studied how cancer cells with POU1F1 overexpression and LDHA blockade could affect tumor growth and glucose uptake." (PMID 33714987, 2021). "Since high LDHA expression can reduce the oxygen dependency of tumour cells by promoting efficient anaerobic/glycolytic metabolism, targeting LDHA is a potential anti-tumour strategy." (PMID 33407546, 2021). "In contrast, LDHA is indispensable to tumor-reactive T cells following adoptive transfer." (PMID 34203136, 2021). "As expected, the glycolic inhibitors 2-DG and 3-BP or depletion of LDHA, which could catalyze the last step of glycolysis, partially abrogated cell proliferation and tumor growth." (PMID 34660259, 2021). "Therefore, immune cell evasion in these cancer models was dependent on the levels of expression of lactate dehydrogenase A (LDHA) in tumor cells and the levels of lactate within the TME, which dampened the cytotoxic effects of NK cells." (PMID 35008348, 2021). "An altered lipid metabolism mediated by a LDHA/B double knockout results in a decreased presence of the Hsp70-anchoring glycosphingolipid Gb3 on the cell surface of tumor cells, which, in turn, reduces the membrane Hsp70 density and increases the extracellular Hsp70 levels." (PMID 34359663, 2021).